MICA (MHC class I polypeptide-related sequence A)
Diseases named in the same sentence as MICA in open-access papers (continued):
Sharing a sentence is not in itself a finding about the gene and the disease.
celiac disease (7 papers, 2005 to 2024). An autoimmune genetic disorder with an unknown pattern of inheritance that primarily affects the digestive tract. "The aim of this study was to investigate anti-MICA antibody formation in patients with celiac disease and its association with other autoimmune processes." (PMID 24565339, 2014). "The microsatellites TNFa1b5 tag the AH18.2 defined by the characteristic alleles of five markers (D6S273*2, BAT2*2, TNFa1b5, MICA*4) in our families with IgA deficiency and celiac disease." (PMID 15842729, 2005). "Increased MICA expression on the intestinal epithelium in active celiac disease via a pathway involving IL-15 induction by gliadin triggers activation of intraepithelial T cells, allowing for the killing of intestinal epithelial cells." (PMID 29973929, 2018). "MHC class I polypeptide-related sequence A (MICA) is highly expressed in the enterocytes of patients with celiac disease, which arises in response to gluten." (PMID 24565339, 2014). "MICA has been also suggested to play a role as target molecule of the innate response in the intestinal mucosa in active Celiac Disease (CD)." (PMID 24058482, 2013). "In healthy individuals MICA seems to be largely inside the cell, however in celiac disease (CD) MICA expression is increased and redistributes to the cell surface where it can provoke autoimmune attack and villous atrophy." (PMID 19223974, 2009). "Both RAET1G1 and MICA showed increased expression in the gut of patients with celiac disease." (PMID 19223974, 2009). "Details of the MICA/B expression pattern showed that the expression was observed not only on epithelial cells but also in the cytoplasm of intraepithelial T lymphocytes in patients with active celiac disease, suggesting extensive stress conditions are present in active celiac disease." (PMID 29973929, 2018).
chronic hepatitis C (7 papers, 2012 to 2024). "A study conducted in a large cohort of chronic hepatitis C patients with Caucasian ancestry demonstrated that MICA rs2596542 was associated with liver fibrosis progression." (PMID 39201329, 2024). "Levels of sMICA were highly correlated to liver disease severity in chronic hepatitis C patients who carried the MICA rs738409 A allele." (PMID 28427234, 2017). "Serum level and single nucleotide polymorphism at rs2596542 of MICA were tested for the association with liver fibrosis in 319 biopsy proven chronic hepatitis C patients." (PMID 28427234, 2017). "MICA was identified from the first GWA study of HCV-related HCC in Japanese chronic hepatitis C patients as a SNP in the 5′ flanking region on chromosome 6, rs2596542, which was positively associated with the progression of chronic hepatitis C to HCC." (PMID 39201329, 2024). "Genetic risk of HCC was associated with MICA expression in chronic hepatitis C patients as well as patients with HBV infection, thereby indicating hypofunction of anti-HCC immunity by MICA insufficiency as a therapeutic target." (PMID 29721164, 2018). "Hence, the pathophysiological effects of MICA SNPs represent a prognostic biomarker for patients with chronic hepatitis C-induced HCC." (PMID 29731972, 2018).
Crohn disease (7 papers, 2009 to 2025). A gastrointestinal disorder characterized by chronic inflammation involving all layers of the intestinal wall, noncaseating granulomas affecting the intestinal wall and regional lymph nodes, and transmural fibrosis. "Others have previously shown that in the normal gut MICA is found largely inside the cell, however increased expression and/or redistribution of protein to the cell surface may occur in autoimmune conditions such as CD and Crohn's disease." (PMID 19223974, 2009). "Moreover, studies have shown that MICA is significantly upregulated in the intestinal epithelial cells of patients with Crohn’s disease (CD) and ulcerative colitis (UC) and may participate in the pathogenesis of inflammatory bowel disease (IBD) via NKG2D–MICA interactions." (PMID 39866909, 2024). "In addition, it has been shown in patients with Crohn’s disease, a chronic inflammatory disorder, that CD4+NKG2D+ TEM cells can kill target cells that express MICA via NKG2D–MICA interaction." (PMID 25352848, 2014).
nasopharyngeal carcinoma (7 papers, 2012 to 2023). A carcinoma arising from the nasopharyngeal epithelium. "For the MICA‐129 polymorphism, studies have shown that it is associated with diseases such as ankylosing spondylitis, cancer, nasopharyngeal carcinoma and chronic graft‐versus‐host disease." (PMID 33017098, 2020). "Like axitinib, other TKIs such as sorafenib and sunitinib have been described to induce the expression of MICA/B in nasopharyngeal carcinoma cells, but their association with a senescent phenotype was not reported." (PMID 26474283, 2015). "A previous report has indicated the deletion of the entire MICA locus in 3.2% of Japanese population and this deletion was shown to be associated with the risk of nasopharyngeal carcinoma (NPC), especially in male." (PMID 23593449, 2013).
neuroblastoma (7 papers, 2012 to 2024). Neuroblastoma (NB) is the most common solid, extracranial childhood tumor. "Increased MICA/B secretion is seen in the context of chemotherapy-induced senescence in neuroblastoma cells, and leads to increased MICA/B binding to surrounding natural killer cells, inhibiting these cells and allowing immune evasion." (PMID 38891878, 2024). "The release of MICA/B was significantly increased in all four different neuroblastoma cell lines compared to the control group after drug-stimulated senescence." (PMID 35309907, 2022). "In this study, we examined the release of the NKG2D ligand MICA/B in different neuroblastoma cell lines before and after treatment with a low dose of chemotherapeutic drug." (PMID 35309907, 2022). "In pediatric patients with neuroblastoma tumor cells escaped from immune surveillance by releasing of soluble MICA (ligand MHC class I-chain-related gene A) compromising NKG2D-dependent NK cell cytotoxicity." (PMID 23730623, 2013). "In summary, chemotherapy-induced senescence in neuroblastoma cells inhibits NK cell recognition via direct secretion of MICA/B or delivery of this ligand in the form of exosomes, which acts on adjacent NK cells to form a suppressive immune microenvironment, thus achieving immune escape." (PMID 35309907, 2022). "Patients with neuroblastoma show high serum soluble MICA (sMICA)associated with the downregulation of surface NKG2D in normal peripheral blood CD8+ cells, decreased NK-mediated killing of MICA+ neuroblastoma cells, HLA class I antigen-deficiency and defects in antigen processing." (PMID 25759690, 2015). "Thus, we co-cultured RNA-modified CD4pos T cells with two sera of neuroblastoma patients containing high detectable levels of MICA (171 and 494 pg/ml; “NB1” and “NB2” respectively)." (PMID 22355347, 2012). "The results showed that different neuroblastoma cell lines showed increased secretion of the NKG2D ligand MHC class I polypeptide-related sequence A/B (MICA/B) following proteolysis after treatment, with MICA/B subsequently recruited to exosomes to downregulate NKG2D expression in NK cells." (PMID 35309907, 2022).
ankylosing spondylitis (6 papers, 2012 to 2024). An autoimmune chronic inflammatory disorder characterized by inflammation in the vertebral joints of the spine and sacroiliac joints. "Among them, AIF1 and IL23R are associated with decreased risk of ankylosing spondylitis; MICA, MAPK14, and ATF6B are linked to increased risk of ankylosing spondylitis." (PMID 38835753, 2024).
COVID-19 (6 papers, 2020 to 2025). A disease caused by infection with severe acute respiratory syndrome coronavirus 2. "The results of MICA rs1051792 SNP analysis revealed that the A/Met allele can be associated with COVID-19 severity, as was detected in all hospitalized patients." (PMID 41153412, 2025). "We compared the alleles and genotypes of MICA in COVID-19 patients versus healthy controls and analyzed their relation to disease severity." (PMID 35805975, 2022). "The result showed a statistical difference with a higher allele frequency of MICA*A9 in COVID-19 patients versus the population reference group (p = 0.004, Pc = 0.025, odds ratio = 1.399, 95% confidence interval = 1.110–1.762)." (PMID 35805975, 2022). "MICA promoter allele rs2596541/C is underrepresented in COVID-19[-] individuals when compared to symptomatic patients (p = 0.0034, OR = 1.9) and to the paired population sample (p = 0.0168) and overrepresented in the COVID-19[+] when compared to its paired population sample (p = 0.0331)." (PMID 34650566, 2021). "Results obtained within this study indicate that the presence of deletion within the NKG2C/KLRC2 gene, as well as NKG2A rs7301582, HLA-E rs1264457, MICB rs065075, and MICA rs1051792 SNPs, could be associated with COVID-19 susceptibility and the severity of the disease." (PMID 41153412, 2025). "For instance, in our previous work, we reported an association between the A*9 STR polymorphism in the MICA gene—an activating ligand for NK cells—and both SARS-CoV-2 infection and the development of symptomatic COVID-19." (PMID 40650195, 2025). "Currently, we have studied the association of COVID-19 with STR in exon 5 of the MICA gene, HLA-B genes, and HLA-B/MICA haplotypes and in asymptomatic, moderate, and severe COVID-19 patients." (PMID 35805975, 2022). "We then analyzed the MICA*A9 haplotypes together obtaining a statistical difference (Pc = 0.01) between COVID-19 patients versus the population reference group." (PMID 35805975, 2022). "Functional assays will provide the means to test the hypothesis of differential NK cell activity between COVID-19 symptomatic and asymptomatic exposed individuals, involving MICA and MICB." (PMID 34650566, 2021). "Host genetics influencing NK cell activation due to differential expression of MICA and MICB is another layer in the complex interaction between the human genome and COVID-19 outcome." (PMID 34650566, 2021). "Our hypothesis is that MICA molecules are very important for the activation of NK and T cells via NKG2D in infectious processes, such as COVID-19." (PMID 35805975, 2022).
inflammatory bowel disease (6 papers, 2009 to 2024). A spectrum of small and large bowel inflammatory diseases of unknown etiology. "Across the epithelial cells, DAEC strains also induce the expression of MICA, which is potentially responsible for mediating inflammatory bowel disease (IBD)." (PMID 34576083, 2021).
lymphoma (6 papers, 2014 to 2024). A malignant (clonal) proliferation of B- lymphocytes or T- lymphocytes which involves the lymph nodes, bone marrow and/or extranodal sites. "Interestingly, romidepsin increased the expression of MICA/B on lymphoma cells to activate CAR-NK cells via NKG2D activating receptor." (PMID 38726000, 2024). "We therefore examined whether lymphoma exosomes carried MICA/B and if exposure to these exosomes or extracellular survivin protein would alter NKG2D levels." (PMID 33513976, 2021). "This specific abnormality is of great interest since lymphoma cells express the stress ligands MICA/B and ULBP, but may escape to NK cytotoxicity due to impaired NKG2D expression." (PMID 25908934, 2014). "Our group has shown that treating KSHV-infected PEL or certain EBV-infected lymphoma B-cell lines with Pom leads to the upregulation of important immune surface markers including ICAM-1, B7-2, MICA, and MHC-I19." (PMID 37463943, 2023). "Analysis of exosome-coated aldehyde beads by flow cytometry did not detect expression of MICA/B, although the parent lymphoma cells did express this NKG2D ligand." (PMID 33513976, 2021). "The NKG2D ligands MICA/MICB/ULBP are stress molecules expressed on tumor cells, and secreted at high levels in HIV patients, leading to down-regulated NKG2D expression on NK and impaired anti-lymphoma cytotoxicity." (PMID 25908934, 2014). "This study established that these lymphoma exosomes contained survivin and FasL but were negative for MHC class I-related chains (MIC)/B (MICA/B) and TGF-β." (PMID 33513976, 2021). "These lymphoma exosomes were also high in MHC class I markers but had no detectable TGF-β and MICA/B." (PMID 33513976, 2021). "In a research on lymphoma, it was found that lymphoma-derived exosomes are enriched in Fas-L and Survivin, a member of the inhibitor of apoptosis (IAP) proteins, but did not contain MICA/B and TGF-b." (PMID 35031075, 2022).
malignant glioma (6 papers, 2008 to 2023). A grade III or grade IV glioma arising from the central nervous system. "Secondly, transforming growth factor-β (TGF-β), a tumor cytokine, has been reported to selectively suppress the transcription and protein expression of MICA, ULBP2 and ULBP4 on malignant glioma cells." (PMID 28159927, 2017). "According to the multivariate role of STAT3 in the immune escape too, interestingly SR141716 lead also to the functional and selective expression of MICA/B on the surface of responsive malignant glioma cells, but not on NHA." (PMID 26008966, 2015). "Additionally, transforming growth factor-beta (TGF-beta) selectively downregulates the expression of MICA, ULBP2, and ULBP4, but not MICB, ULBP1, or ULBP3, in malignant glioma cells." (PMID 24885711, 2014).
type 1 diabetes (6 papers, 2012 to 2023). "Of the remaining five genes, three [MICA, NCR3, and TAP2] have been previously associated with type 1 diabetes, while APOM and HLA-DRB5 have been associated with RA." (PMID 32245788, 2020). "For example, among the strongest associations with the lead SNPs at the following loci include: CLEC16A, CD28, MICA, and ELMO1 with eosinophil counts; AHI1 with monocyte and neutrophil counts, asthma, and hay fever (also shared by CD28); and MICA with type 1 diabetes." (PMID 37120605, 2023).
ulcerative colitis (6 papers, 2020 to 2025). An inflammatory bowel disease involving the mucosal surface of the large intestine and rectum. "The MICA*007 allele was reportedly associated with AS and ulcerative colitis (UC), while MICA*019 was associated with AS and Bechet’s disease." (PMID 34208618, 2021).
endometriosis (5 papers, 2015 to 2025). The growth of functional endometrial tissue in anatomic sites outside the uterine body. "The increase in soluble MICA/B levels in the peritoneal fluid of patients with endometriosis negatively affects the cytotoxic function of NK cells." (PMID 40508002, 2025). "MICA was detected in 82 (67.8%) endometriosis-affected women and in 58 (71.6%) controls (P = 0.641)." (PMID 25775242, 2015). "It is possible that the results may not be fully representative of the ligand environment in endometriosis, whereby some allelic variants of MICA are not shed into the peritoneal space, and thus compensate for the absence of other allelic forms." (PMID 36613776, 2022). "Clinical, surgical and biological correlations with peritoneal fluid MICA, MICB and ULBP-2 levels in women with endometriosis are expressed in S3 Table." (PMID 25775242, 2015). "For this reason, we assayed peritoneal fluid NKG2DLs (MICA, MICB and ULBP-2) obtained from patients with histologically proven endometriosis and endometriosis-free women." (PMID 25775242, 2015). "Statistical analyses for peritoneal NKG2D ligands (MICA, MICB and ULBP-2) ratio levels in women with endometriosis and controls." (PMID 25775242, 2015). "When samples with undetectable peritoneal fluid levels of MICA, MICB and ULBP-2 were excluded, MICA ratio levels were significantly higher in endometriosis patients than in controls (median, 1.1 pg/mg; range, 0.1–143.5 versus median, 0.6 pg/mg; range, 0.1–3.5; p=0.003)." (PMID 25775242, 2015).
HCMV infection (5 papers, 2014 to 2022). "We concluded that, although HCMV activates MICA cell surface expression, this response is counteracted in the context of productive HCMV infection by the action of a previously uncharacterized function." (PMID 24787765, 2014). "However, during HCMV infection, MICA expression is strongly induced perhaps overwhelming this slow process of degradation." (PMID 33939764, 2021). "We next wanted to address MICA*008 maturation and degradation dynamics during HCMV infection." (PMID 33939764, 2021). "Since we observed that the US9 SP was sufficient for targeting MICA*008, we wondered whether the same would be true during HCMV infection." (PMID 33824318, 2021). "For example, in HCMV infection some MICA alleles are downregulated while MICA*008 is not." (PMID 35805975, 2022). "We therefore wondered whether UL147A would induce MICA*008 degradation during HCMV infection." (PMID 33939764, 2021). "Indeed, it has been proposed that this degree of MICA/B diversity may have been selected as a mechanism by which cells evade HCMV infection." (PMID 24787765, 2014). "We therefore concluded that the US9 SP was the most significant MICA*008-targeting domain of US9, even in the context of HCMV infection." (PMID 33824318, 2021). "During HCMV infection, UL147A and US9 act additively, each reducing MICA*008 surface expression by ~2–4 fold, with their combined effect reaching ~10-15-fold reduction." (PMID 33939764, 2021). "UL147A primarily induces MICA*008 maturation arrest, and additionally targets it to proteasomal degradation, acting additively with US9 during HCMV infection." (PMID 33939764, 2021). "In fact, MICA and MICB have been reported to be regulated by endogenous miRNAs in tumors and following cytomegalovirus infection." (PMID 26878797, 2016). "In the context of an HCMV infection, deletion of US18 and US20 led to an increase MICA/B levels as monitored by immunoblotting." (PMID 24787765, 2014). "MICA levels increased by more than 15-fold in cells infected with double mutant BAC20 ΔUS9 compared to BAC2-infected cells, confirming the additive roles of US9 and UL147A during HCMV infection." (PMID 33939764, 2021). "Hence, we concluded that the increase in NK-mediated killing of cells infected with BAC2 ΔUL147A or BAC2 ΔUS9 is due to changes in MICA*008 levels, confirming UL147A functionality during HCMV infection." (PMID 33939764, 2021). "We previously reported that the bulk of MICA*008 was retained in the ER during HCMV infection, and that US9 did not lead to appreciable differences in total MICA*008 quantity in HCMV-infected cells." (PMID 33939764, 2021). "At no stage during the replication cycle did HCMV infection induce an up regulation MICA, MICB, or ULBP2 expression at the cell surface." (PMID 24787765, 2014).